PXDN (peroxidasin)
Diseases named in the same sentence as PXDN in open-access papers (continued):
Sharing a sentence is not in itself a finding about the gene and the disease.
infection (5 papers, 2015 to 2024). The state of being infected such as from the introduction of a foreign agent such as serum, vaccine, antigenic substance or organism. "PXDN-deficient mice had markedly diminished survival, with 100% mortality at 24 h following infection while wild-type mice had 44% and 22% survival at 24 and 48 h, respectively." (PMID 29775486, 2018). "Our findings of PXDN killing of GN bacteria, including P. aeruginosa, support therapeutic interventions involving PXDN to augment host defense against such infections." (PMID 29775486, 2018). "We also observed that infection with axenic nematodes affected the expression of genes involved in oxidative stress (Peroxiredoxin, Peroxidasin, Glutathione peroxidase, Stress-activated protein kinase JNK, Hsp22 and several Glutathione S-transferases)." (PMID 26162375, 2015). "Moreover, since PXDN has been linked to anti-tumoral pathways in B-cells, the downregulation of PXDN expression by blv-miR-b4-3p might be involved in BLV tumorigenesis in cattle during natural infection with this virus." (PMID 36730262, 2023). "Knowing that PXDN is involved in anti-tumoral pathways in B-cells, the results presented here suggest that blv-miR-b4-3p might be involved in BLV tumorigenesis during natural infection with BLV in cattle." (PMID 36730262, 2023).
adenocarcinoma (1 paper, 2023). A common cancer characterized by the presence of malignant glandular cells. "We found that higher expression of PXDN was significantly associated with shorter survival of adenocarcinoma patients (hazard ratio (HR) = 1.57; 95% confidence interval (CI), 1.05–2.37; P = 0.028, log-rank test), whereas that of ADAMTS16 was not." (PMID 37397358, 2023). "Median survival of adenocarcinoma patients was 54.4 months for the low PXDN expression subgroup and 39.0 months for the high PXDN expression subgroup." (PMID 37397358, 2023).
bacterial infection (1 paper, 2020). "One might hypothesize that the inhibitory activity of anti-peroxidasin autoantibodies may contribute to the higher rate of bacterial infection observed in double-positive patients." (PMID 32143501, 2020).
inflammation (1 paper, 2024). Aberrant reaction of the microcirculation characterized by movement of fluid and leukocytes from the blood into extravascular tissues. "As discussed later, peroxidasin plays a role in vascular wall development and possibly cardiovascular inflammation and disease." (PMID 39061857, 2024). "Therefore, it is plausible that in addition to MPO, the upregulation of peroxidasin/VPO1 may also contribute to the pathogenesis of CVD and post-MI cardiac inflammation and dysfunction." (PMID 39061857, 2024).
PXDN also shares sentences with these, for which no sentence is quoted: cardiac hypertrophy (3 papers); diabetes (3); Hypertension (3); pulmonary hypertensive (3); aniridia (2); Borderline personality disorder (2); coronary artery disease (2); COVID-19 (2); kidney disease (2); acute myeloid leukemia (1); Adrenocortical carcinoma (1); aneurysm (1); angina pectoris (1); aortic aneurysm (1); Bladder Urothelial Carcinoma (1); breast tumor (1); cerebellar ataxia (1); cervical squamous cell carcinoma (1); chronic kidney disease (1); colorectal tumors (1); cutaneous melanoma (1); developmental and epileptic encephalopathy (1); developmental delays (1); diarrheal disease (1); endocervical adenocarcinoma (1); esophageal cancer (1); eye inflammation (1); fibrosis (1); genetic diseases (1); Gillespie syndrome (1).
A further 25 diseases each share a sentence with PXDN in 1 paper.